MTOR (mechanistic target of rapamycin kinase)
Diseases named in the same sentence as MTOR in open-access papers (continued):
Sharing a sentence is not in itself a finding about the gene and the disease.
brain tumors (continued). "To determine whether this relationship extends to glial cells in brain tumors, we overexpressed the dominant negative forms of S6K (via S6KKQ) and mTOR (TorTED) in tumor brains using repo-GAL4." (PMID 41252380, 2025). "For this purpose, brain tumor cells upregulate GPD1 to switch the metabolic flow to lipid metabolism by making use of the glycolysis metabolite DHAP, which was also reported to be the only sensor metabolite of the mTOR pathway in glycolysis." (PMID 38273014, 2024). "We assumed brain tumor cells and tumor microenvironment suppressed natural killer (NK) cells via expression of factors such as transforming growth factor (TGF)-β and impairs NK cells by downregulating the mTOR pathway." (PMID 36304453, 2022). "Although several limitations to this theoretical model exist, the consideration of aberrant PIK3/AKT/mTOR signaling in glia during aging elucidates several therapeutic opportunities for brain tumors, including non-pharmacological interventions." (PMID 33472174, 2021). "Rapamycin [mammalian target of rapamycin (mTOR)] is mainly regulated by the phosphoinositide-3-kinase (PI3K)/protein kinase B (Akt) pathway, and is over-activated in both sporadic and hereditary brain tumors, related to cell growth, differentiation and tumorigenesis." (PMID 33042832, 2020). "The mTOR pathway acts as key regulator of cell size and growth control, proliferation, differentiation and survival during brain development, and increasing evidence supports the role of the TOR pathway in a wide variety of neurological disorders including both MCD and brain tumors." (PMID 24858213, 2014). "Approved mTOR inhibitors scored even lower for both everolimus (CNS-MPO: 1.25) and temsirolimus (CNS-MPO: 1.00) suggesting that currently approved drugs have more active mechanisms of brain uptake, or are unlikely to be effective for brain tumors." (PMID 40386392, 2025).
head and neck cancer (69 papers, 2012 to 2026). A primary or metastatic malignant neoplasm affecting the head and neck. "In particular, Lui and co-workers found a PIK3CA mutation in 30.5% of head and neck cancer patients who were sensitive to anti-mTOR treatment." (PMID 24642661, 2014). "mTOR signaling pathway has been found to be activated and expression levels of mTOR and downstream proteins are potential diagnostic and prognostic biomarkers for head and neck cancer." (PMID 23762622, 2012). "Other treatment strategies are currently being pursued, such as dual inhibition of the phosphatidylinositol-3-kinase/mammalian target of rapamycin (P13K/mTOR) pathway or the use of a pan-PI3K inhibitor in association with paclitaxel in NOTCH1-mutant meta- static head and neck carcinoma." (PMID 36611391, 2022). "We found that PIP4K2B positively regulates the mTOR signaling pathway and promotes head and neck cancer cell growth." (PMID 38539515, 2024). "Numerous mTOR pathway components have been documented to be dysregulated in malignancies including breast, colon, ovarian, kidney, and head and neck cancers." (PMID 37999212, 2023). "PI3K/AKT/mTOR signaling is active in head and neck cancers, over 90% of which are squamous cell carcinomas." (PMID 36980552, 2023). "The PI3K/Akt pathway is highly upregulated in head and neck CSCs and therapeutic inhibition of the mechanistic target of rapamycin (mTOR) has shown clinical success in head and neck cancer." (PMID 36726797, 2023). "The mTOR plays a significant role in diverse types of cancer, including hematologic malignancies and prostate, breast, skin, and head and neck cancers." (PMID 36980552, 2023). "The synergism between mTOR inhibitors and cisplatin was previously demonstrated on several different cancer cell types, including head and neck cancer." (PMID 36835812, 2023). "For example, paeoniflorigenone, Paonia suffruticosa-derived natural products, shows antiproliferation, apoptosis, and autophagy in head and neck cancer cells by inactivating PI3K/AKT/mTOR/p70S6K signaling." (PMID 36139919, 2022). "High expression of MMP25 in head and neck cancer is associated with a worse prognosis; MMP25 is related to apoptosis, the KRS signaling pathway, the PI3K/AKT/mTOR signaling pathway, and the JAK/STAT signaling pathway." (PMID 35060926, 2022). "Although there have been a number of reports describing mTOR activation in 80 to 90% of patients with head and neck cancer, little is known about its role in HPV-related OPSCC." (PMID 33482765, 2021). "This study demonstrated activation of the mTOR pathway in HPV-positive head and neck cancer cell lines as well as HPV-negative cell lines in vitro." (PMID 33482765, 2021). "mTOR is an important downstream signal of PI3K/AKT/mTOR signaling pathway activated in head and neck cancer." (PMID 32351329, 2020). "This article also provided an update on several AKT/mTOR inhibitors that emerged as promising candidates for therapeutic interventions against OC/head and neck cancer (HNC) in clinical studies." (PMID 32384682, 2020). "As reported, mTOR and its downstream effectors, eIF-4E, 4EBP1, S6K1, and S6 are all biomarkers for diagnosis and prognosis in head and neck cancer, demonstrating the promising prospect for mTOR inhibitors in HNSCC treatments." (PMID 30754640, 2019). "Our first experiment tested DD‐SR interactions involving mTOR, a key growth regulating kinase in head and neck cancer." (PMID 30858180, 2019). "There is evidence that in head and neck cancer, the NF‐κB transcriptional factor is constitutively activated and linked to activation of known oncogenic pathways, such EGFR/Ras/RAF/MAPK, Akt/PI3K/mTOR, ΙΚΚ/NF‐κB, STAT3 and wnt/β‐catenin." (PMID 29911313, 2018). "Multiple studies have been performed that examine Akt pathway inhibition in other human cancer types, including one study using a dual inhibitor of PI3K and mTOR in human head and neck cancer that demonstrated both in vitro and in vivo anti-neoplastic effects." (PMID 30011343, 2018).
head and neck cancer (continued). "Further studies on different tumor site of head and neck cancer are thus necessary to fully evaluate the effect of mTOR signaling activation." (PMID 28811537, 2017). "Although radioresensitizing using dual PI3K/mTOR inhibitors has been reported in head and neck cancer cell lines, these results only reflect the OSCC tumor subtype and do not truly represent the clinical situation." (PMID 28978144, 2017). "mTOR is activated in more than 80% of head and neck cancers, underscoring its importance as a target for therapy." (PMID 27015118, 2016). "Targeting the PI3K/AKT/mTOR signaling pathway in head and neck cancer was suggested to be promising in improving the treatment efficacy and clinical outcome." (PMID 27533461, 2016). "The phosphatidylinositol 3 kinase (PI3K) / protein kinase B (PKB, also known as AKT) and mammalian target of rapamycin (mTOR) signaling cascade is the most commonly altered signaling cascade in head and neck carcinoma." (PMID 27533461, 2016). "mTOR inhibitors, such as rapamycin and its derivatives temsirolimus and everolimus, exhibit inhibitory effects on head and neck cancer in both in vitro cell line model and in vivo xenograft model." (PMID 23762622, 2012). "mTOR signaling pathway was activated in head and neck cancer, making it attractive for targeted therapy." (PMID 23762622, 2012). "Since mTOR inhibitor alone has displayed inhibitory effects on head and neck cancer, it has potential as a single therapeutic agent." (PMID 23762622, 2012). "mTOR signaling pathway has been found to be activated in head and neck cancer, making it attractive for targeted therapy." (PMID 23762622, 2012). "Combined mTOR inhibitors with radiation, chemotherapeutic agents, or other targeted therapeutic agents would result in synergistic repression on head and neck cancer, thus minimizing their toxicity and overcoming chemoresistant tumors." (PMID 23762622, 2012). "In head and neck cancer, it has been shown that mTOR signaling pathway was activated, making it attractive for targeted therapy." (PMID 23762622, 2012). "A large number of clinical trials have been initiated to evaluate the clinical application of mTOR inhibitors in patients with head and neck cancer." (PMID 23762622, 2012). "Some studies have demonstrated that expression levels of mTOR and downstream targets eIF4E, 4EBP1, S6K1, and S6 are potential diagnostic and prognostic biomarkers for head and neck cancer." (PMID 23762622, 2012). "It was found that phosphorylated mTOR exhibited better sensitivity and specificity than phosphorylated 4EBP1 in differentiating tumor from normal mucosa from patients with head and neck cancer." (PMID 23762622, 2012). "A large number of clinical trials have been initiated to evaluate the therapeutic effects of mTOR inhibitors on patients with head and neck cancer." (PMID 23762622, 2012). "Although some studies have demonstrated the inhibitory effects of mTOR inhibitors on head and neck cancer using in vitro cell line model and in vivo xenograft model, little evidence has been obtained from clinical trials." (PMID 23762622, 2012). "In head and neck cancer, the mutation of EIF4G1 affects the activation of mTOR signaling." (PMID 36897548, 2023). "Proteins in the mTOR pathway could indicate some information on prognosis of patients with head and neck cancers." (PMID 35883491, 2022). "In fact, PI3K/Akt/mTOR signaling pathway was regarded as a potential therapeutic target in head and neck cancer including NPC39–41, and activated PI3K/Akt/mTOR signaling might induce proliferation, migration and invasion in NPC42,43." (PMID 35260638, 2022). "Another meta-analysis including 105 publications and 8630 patients analyses the frequency of PI3kCA (13%), PTEN (4%), mTOR (3%) and Akt (2%) mutations in head and neck cancer, although data stratified by anatomical location are not reported." (PMID 35954497, 2022).
head and neck cancer (continued). "Furthermore, bone marrow mesenchymal stem cells promoted proliferation, invasion, survival, tumorigenicity and migration of head and neck cancer through periostin-mediated PI3K/Akt/mTOR activation." (PMID 34205668, 2021). "In this review, we discuss how these mutant genes could affect mTOR signalling and highlight their impact on metabolic processes, as well as suggest potential targets for therapeutic intervention, primarily in head and neck cancer." (PMID 30970654, 2019). "These incongruous findings suggest that mTOR signaling may be various in different tumor site of head and neck cancer." (PMID 28811537, 2017). "In addition, mTOR and downstream targets eIF4E, 4EBP1, S6K1, and S6 are potential diagnostic and prognostic biomarkers for head and neck cancer." (PMID 23762622, 2012). "mTOR inhibitor has potential as a single therapeutic agent or in combination with radiation, chemotherapeutic agents, or other targeted therapeutic agents to obtain synergistic repression on head and neck cancer." (PMID 23762622, 2012). "In addition, expression levels of mTOR and downstream targets eIF4E, 4EBP1, S6K1, and S6 are potential diagnostic and prognostic biomarkers for head and neck cancer." (PMID 23762622, 2012). "Furthermore, some studies have demonstrated that combined mTOR inhibitors with radiation, chemotherapeutic agents, or other targeted therapeutic agents resulted in synergistic repression on head and neck cancer." (PMID 23762622, 2012). "Furthermore, mTOR inhibitors exhibit inhibitory effects on head and neck cancer." (PMID 23762622, 2012). "In head and neck cancers include NPC, the PI3K/mTOR pathway stands out as the most activated signaling pathway." (PMID 38272224, 2024). "It was reported that in head and neck cancer cells, HPA induces autophagy via suppressing mTOR signaling." (PMID 35970822, 2022). "In head and neck cancers, CCL19/CCR7 activation produced phosphorylation of mTOR that elevated cell survival." (PMID 35203305, 2022). "For instance, in a study on the inhibitor (BGT226) of the phosphoinositide-3-kinase/mammalian target of rapamycin (PI3K/mTOR) signaling pathway, the drug treatment led to cell death via autophagy in head and neck cancer cells." (PMID 33525678, 2021). "Despite reports of a link between human papillomavirus (HPV) infection and mechanistic target of rapamycin (mTOR) signaling activation, the role of the mTOR pathway, especially raptor and rictor, in HPV-related head and neck cancer is still unclear." (PMID 33482765, 2021). "In the present study, we evaluated the interest of inhibiting the EGFR/mTOR/HIF-1 axis to radiosensitize head and neck cancer cells based on combining the anti-EGFR monoclonal antibody cetuximab and the mTOR inhibitor rapamycin." (PMID 31640284, 2019). "The two critical oncogenic pathways, Akt/mTOR and IKK/NF-κB, are constitutively active in both human head and neck cancer specimens as well as cell lines." (PMID 26895469, 2016). "Next, mTOR, Raptor and Rictor were knocked down in two other head and neck cancer cell lines, UMSCC25 and O28, and its effects on NF-κB, mTOR, and Akt activity were examined." (PMID 26895469, 2016). "For instance, in vivo studies in mice, targeting the mTOR and IGF molecules, have shown promising results for head and neck cancer treatment." (PMID 23950933, 2013). "mTOR is an important downstream signal of PI3K/AKT/mTOR signaling pathway and it is activated in head and neck cancer." (PMID 23762622, 2012). "For instance, S100A11 knockdown causes a decrease in phosphorylated PI3K, phosphorylated Akt, and phosphorylated mTOR and disturbs cell proliferation and migration in head and neck carcinoma cells, indicating that the upregulation of S100A11 activates the PI3K–Akt-mTOR pathway in these tumor cells." (PMID 36835331, 2023).
head and neck cancer (continued). "Moreover, paeoniflorigenone-inhibiting PI3K/AKT/mTOR/p70S6K signaling leads to a suppression of necroptosis by inactivating necroptotic proteins (RIP and MLKL) in head and neck cancer cells." (PMID 36139919, 2022). "Our previous studies showed that plumbagin could inhibit the growth, invasion and migration of head and neck cancer by inhibiting PI3K/Akt/GLUT1, p38 MAPK, and PI3K/Akt/mTOR-mediated pathways." (PMID 32974176, 2020). "Similarly, recent studies in lung and head neck cancer cell lines have known significant synergism when FGFR and MTOR signaling are simultaneously inhibited." (PMID 28008155, 2017). "Rapamycin and AKT inhibitor uniformly abrogated mTOR inhibition-induced AKT activation but failed to induce antitumor responses in a subset of head and neck cancers ex vivo." (PMID 25170609, 2014). "Since high EGFR expression is a negative prognostic factor, associated with lower progression-free and overall survival rates, we reasoned that resistant head and neck cancer cells could be re-sensitized to ionizing radiation by targeting EGFR and mTOR with cetuximab and rapamycin, respectively." (PMID 31640284, 2019). "Notably, mTOR inhibitors concurrent with standard-of-care chemoradiotherapy have been shown to increase cell killing and prolong survival in an animal model of HPV-positive head and neck cancer." (PMID 28422732, 2017). "Our findings reveal a new mechanism by which EGFR/PI3K/Akt/mTOR signaling promotes head and neck cancer progression and underscores the need for developing a therapeutic strategy for targeting IKK/NF-κB either as a single agent or in combination with cisplatin in head and neck cancer." (PMID 26895469, 2016). "Notably, inhibition of mTOR signaling (mTORC1 and mTORC2) results in restoration of normal BMAL1 levels in the epidermis in vivo, and also in head and neck cancer cells." (PMID 27285754, 2016).
hyperlipidemia (69 papers, 2011 to 2026). "Abundant maternal OA, as is seen in the second half of human pregnancy due to the well described hyperlipidemia of late gestation, would lead to activation of mTOR causing the stimulation of amino acid uptake and transfer to the fetus." (PMID 38223199, 2024). "Side effects associated with the clinically used mTOR inhibitors include increased risks of stomatitis (mouth ulcers), diarrhea and nausea, hyperlipidemia, and infection (presumably due to immune suppression)." (PMID 24379984, 2013). "Hyperlipidemia caused by mTOR inhibitors is repeatable, reversible, and dose-dependent." (PMID 36615165, 2023). "However, withdrawal of mTOR inhibitor is associated with rapid tumor regrowth, and mTOR inhibitors use is burdened with significant adverse events, including infections, mouth ulcers, and hyperlipidemia." (PMID 26220190, 2015). "Hypothesized that hyperlipidemia during treatment with mTOR inhibitors might be an epiphenomenon associated with slowed tumor growth rather than as a marker of drug efficacy." (PMID 25885920, 2015). "The pathogenesis of hyperlipidemia associated with mTOR inhibitor may be related to decreased degradation of apolipoprotein B100." (PMID 24599185, 2014). "Moreover, the mechanism underlying its treatment of hyperlipidemia may be through regulating the PI3K/AKT/mTOR/SREBP‐1 pathway to inhibit de novo lipid synthesis." (PMID 40928061, 2026). "Ginsenoside Rg1 protected podocytes from hyperlipidemia-induced damage via targeting the mammalian target of rapamycin (mTOR)/NF-κB/NLRP3 Axis by adopting L-leucine (LEU), the activator of mTOR." (PMID 39000237, 2024). "Anticancer drugs that inhibit phosphoinositide 3-kinase (PI3K)/Akt/mammalian target of rapamycin (mTOR) signaling has been discovered to induce hyperlipidemia." (PMID 37612751, 2023). "In order to investigate the effect of PCSK9 inhibitors on mTOR inhibitors-induced hyperlipidemia, the liver of the mice was collected for analysis on the twelfth day after the first drug treatment." (PMID 37896137, 2023). "As thrombocytopenia and hyperlipidemia are known adverse events in humans treated with rapamycin and other mTOR inhibitors, continued monitoring of these parameters in future studies of rapamycin in dogs is indicated." (PMID 37275618, 2023). "Ezra E W Cohen and his colleague recruited 138 cancer patients and found that 43% of those treated with mTOR inhibitors developed hyperlipidemia." (PMID 37896137, 2023). "In the present study, we show that the use of mTOR inhibition in patients with TSC is associated with a significant and stable increase in the prevalence of hyperlipidemia." (PMID 35804402, 2022). "in observational studies, an incidence of mTOR-inhibitor-related hyperlipidaemia of up to 75% has been reported." (PMID 36009482, 2022). "Our previous data indicated that the administration of CO significantly improves HFD-induced hyperlipidemia by reprogramming the gut microbiota composition and inhibiting the mTOR pathway and biosynthesis of lipid-related genes." (PMID 35745155, 2022). "For instance, various compounds from 70% ethanolic extract of Trigonella foenum-graecum L seeds mainly work by affecting the activation of the EGFR/AKT/mTOR signaling cascade in the treatment of hyperglycemia and hyperlipidemia." (PMID 34987591, 2021). "Microalbuminuria was present in 121 patients (42.5%) and was associated with higher systolic blood pressure, use of antihypertensive medications, hyperlipidemia, higher blood creatinine, higher BMI, a living donor, and the use of mTOR inhibitors." (PMID 33912576, 2021). "Rg1 significantly inhibited pyroptosis, restored nephrin expression and cytoskeletal structure in the podocytes, and blocked hyperlipidemia-induced mTOR/NF-κB signaling." (PMID 33133213, 2020). "Ginsenoside Rg1 protects podocytes from hyperlipidemia-induced damage by inhibiting pyroptosis through the mTOR/NF-κB/NLRP3 axis, indicating a potential therapeutic function in DN." (PMID 33133213, 2020).